ENSG00000251735
Gene: Small nucleolar RNA gene on chromosome 14 (46,960,423 to 46,960,546, forward strand). Ensembl gene ENSG00000251735.
Homologues: Orthologues: mouse Gm55141 (65% identical). Paralogues in human: SNORA25 (74% identical), SNORA25B (72% identical).